MBL2 (mannose binding lectin 2)
Diseases named in the same sentence as MBL2 in open-access papers (continued):
Sharing a sentence is not in itself a finding about the gene and the disease.
infection (continued). "Regarding the type of infection, gram-positive bacteria were more frequent in the MBL2 variant group, 47.4% versus 26.4%, RR = 1.8 (95% CI: 0.9-3.4, p = 0.09)." (PMID 24886325, 2014). "So far, there are few studies describing the incidence of infections in ASCT related to MBL2 gene variants." (PMID 24886325, 2014). "The focus of this study is the association between MBL2 gene variants and the risk of infections in patients with different hematologic diseases undergoing ASCT." (PMID 24886325, 2014). "Although not statistically significant, there was a higher incidence of major infections in the MBL2 variant group as well as a higher number of infections caused by gram-positive bacteria." (PMID 24886325, 2014). "When the incidence of infections caused by different microorganisms was analyzed, a higher number of infections caused by gram-positive bacteria was found in patients carrying the variant MBL2 form, and these were mainly staphylococci." (PMID 24886325, 2014). "In this respect, the incidence of infections caused by Staphylococcus epidermidis was greater in the MBL2 variant group." (PMID 24886325, 2014). "Inherited MBL insufficiency, which leads to impaired innate immune function and enhanced susceptibility to infection, is essentially caused by three structural variants in exon 1 of MBL2 gene." (PMID 25654073, 2014). "In our series, the incidence of mortality due to infection was higher in the MBL2 variant form, and the cause of death in all patients was major infection." (PMID 24886325, 2014). "Most infections caused by gram-positive bacteria occurred in the early period and were more frequent in the variant MBL2 group (42.1% versus 26.4% in the MBL2 wild-type group, p = 0.2)." (PMID 24886325, 2014). "In this MBL2 variant group infection was more frequently the cause of mortality than in the MBL2 wild-type group (p=0.05)." (PMID 24886325, 2014). "The average time in days until the first infection after the transplantation day was 7.98 days (SD = 11.34) in the wild-type MBL2 group and 13 days (SD = 30.73) in the MBL2 variant group (p = 0.32)." (PMID 24886325, 2014). "There was a greater incidence of infections caused by Staphylococcus epidermidis in the MBL2 variant group, 36.8% versus 17%, RR = 2.2 (95% CI: 0.9-5.0, p = 0.11)." (PMID 24886325, 2014). "MBL2 had previously shown associations with different disturbances in the lung function, infection risk, and survival of CF patients." (PMID 24603877, 2014). "Here, we sought to study the association of plasma MBL levels and MBL2 coding and promoter region genotypes to infection, type of infection and, febrile episodes in adults with chemotherapy induced neutropaenia." (PMID 22363494, 2012). "In this preliminary study, MBL2 haplotypes or SNPs linked to them were associated with the susceptibility to infection and with parasitaemia control of asymptomatic adults." (PMID 19432958, 2009). "In this preliminary study, MBL2 haplotypes or SNPs linked to them were found associated with susceptibility to infection and parasitaemia control of asymptomatic adults." (PMID 19432958, 2009). "Larger, prospective studies should be conducted to gain further insight into the hypothesized immunological redundancy of antibodies and its effect on infection when an individual has an MBL2 genotype coding for low or deficient MBL." (PMID 36012556, 2022). "However, the previous study did not examine any association between the clinical and serological subgroups, including the subtype of GBS, recent infection with C. jejuni and auto-antibodies, with MBL2 polymorphisms or serum MBL levels." (PMID 35388043, 2022). "Multiple genetic epidemiological studies reported that the presence MBL2 derived alleles and genotypes are associated with an increased risk to infections and might be considered as a prognostic marker in various infectious conditions." (PMID 31941497, 2020).
infection (continued). "Likewise, infants with variant MBL2 genotype would carry an increased risk for infection during early childhood." (PMID 28558032, 2017). "It is thus hard to mechanistically understand how such complex interactions could be affected by MBL2 polymorphisms which are well correlated to susceptibility to infections." (PMID 26977272, 2016). "Polymorphisms of the human MBL2 gene are associated with deficiency of serum MBL protein levels that may cause susceptibility to infection." (PMID 26684757, 2015). "Frequency distribution of genotype and alleles of VDR and MBL-2 gene varies among different ethnic population, which may lead to variable susceptibility to the infection." (PMID 26693353, 2015). "ASCT patients with MBL2 variant genotypes are more likely to die as a result of an infection." (PMID 24886325, 2014). "It would be reasonable to assess whether early antifungal prophylaxis in our ASCT patients with the MBL2 variant gene could reduce the incidence of such infections." (PMID 24886325, 2014). "However, all deaths in the variant MBL2 group were related to infection, whereas in the wild-type MBL2 group, deaths were due to other causes, with a p-value of 0.05 at the limit of statistical significance." (PMID 24886325, 2014). "Results were analyzed according to MBL2 genotype, comparing normal homozygous patients (AA) and patients with AO and OO genotype and to determine if there were differences between the two groups in terms of demographic characteristics, underlying disease, infection parameters and mortality." (PMID 24886325, 2014). "By introducing these subgroups, we were able to investigate the role of the MBL2 SNPs in different possible stages of infection." (PMID 36012556, 2022). "Nonetheless, other studies involving Allo-HSCT showed contradictory results regarding the influence of MBL2 polymorphisms and MBL deficiency on infection risk." (PMID 31706269, 2019). "Comparison between the control and the infected pups showed a significant increase of IL-17A levels at day 60 post infection (i.e. 64 days old), whereas Mbl2 was significantly upregulated at days 21 and 60 post infection (i.e. 25 and 64 days old respectively)." (PMID 31222079, 2019). "Recipients with low-producer MBL2 genotypes (AO and OO genotypes) had a tendency to have more episodes of infection (2.42, SD = 1.84) than those with MBL2 wild-type genotype (AA genotypes) (1.74, SD = 1.04), p = 0.05." (PMID 31706269, 2019). "As only a minority of infections appears influenced, we postulate that genotype-based MBL2 levels only play a minor role in the complex situation of immunological maturation of preterm infants." (PMID 28558032, 2017). "In our study, we identified a significant association between the donor MBL2 rs11003125 genotype and bacterial infection after LT (P = 0.024), with recipients of livers with the MBL2 rs11003125 GG genotype being more prone to infection (OR = 3.941)." (PMID 27063552, 2016). "Our data show that infection was accompanied by the up-regulation of c1qa and ptx3 as well as the down-regulation of mbl2." (PMID 27100179, 2016). "We studied the genetic polymorphisms in the Exon 1 (alleles A/O) and promoter region (alleles Y/X; H/L, P/Q) of the MBL2 gene, in SCD patients as an increased incidence of infections is seen in these patients." (PMID 26977272, 2016). "Several studies have been conducted worldwide including several African populations looking at MBL2 genetic variants and plasma/serum MBL concentration and their association to increased infection susceptibility." (PMID 25830474, 2015). "A regression model was constructed for each type of infection, with infection-related variables being the outcome and the independent variable being the MBL2 genotypes, adjusted for sex, age, hematologic disease, active pre-transplant hematologic disease." (PMID 24886325, 2014).
infection (continued). "We studied the role of polymorphic variants at the genes of MBL (MBL2), SP-A1 (SFTPA1), SP-A2 (SFTPA2), and SP-D (SFTPD) in 93 patients with H1N1 pandemic 2009 (H1N1pdm) infection." (PMID 24950659, 2014). "This prospective study focused on comparing the incidence of infection and mortality after ASCT between patients with the wild-type MBL2 genotype compared to patients carrying a variant MBL2 genotype." (PMID 24886325, 2014). "In summary, the results of our study suggest that ASCT patients with the MBL2 variant gene have increased fungal infections, which would suggest that MBL offers protection against such infections." (PMID 24886325, 2014). "Mannose binding lectin 2 (MBL2) is an important component of the first-line defense against infections." (PMID 22220182, 2011). "MBL2, found in amniotic fluid, is a serum protein involved in the activation of the complement system of the innate immune system and plays a role in fetal inflammatory response to infection and injury." (PMID 31253109, 2019). "In a large cohort of VLBWI MBL2 deficiency had no major impact on infection risk unless children were born between 32 0/7 and 36 6/7 weeks of gestation." (PMID 28558032, 2017). "In comparing the groups with and without infection, the SNPs most significantly associated with infection were located in complement genes, including C3, C5, C6, C7, C9 and MBL2 (P < 10−6)." (PMID 27063552, 2016). "There was only 1 case of infection by Staphylococcus aureus, in the MBL2 wild-type group." (PMID 24886325, 2014). "In contrast, a plethora of case-control association studies has attributed a role of MBL variability to infection phenotypes, and the common belief now is that MBL2 variability has arisen as a consequence of human contact with pathogenic microorganisms in diverse geographic environments." (PMID 21695215, 2011). "None of the LYPA-similar haplotypes were associated with the infection, and so the association would not have been revealed by conventional MBL2 typing techniques." (PMID 19432958, 2009). "On the other hand, Zachariah and collaborators (2016) observed that SCD patients who present mutant alleles for MLB2 had a greater rate of microbiological infections, despite the allelic frequencies of MBL2 having no substantial differences between control and SCD groups." (PMID 39846606, 2025). "Three common MBL2 exon 1 mutations (sometimes designated as B, C, and D) encode unstable MBL polypeptides with subnormal molecular weight, blood levels, oligimerization, ligand binding, and complement activation and limited acute-phase responses to severe infection." (PMID 31117958, 2019). "However, the small number of published articles and small sample sizes emphasizes the need for a broader evaluation, taking into account the ethnic differences of populations infected by HTLV-1 in order to better understand the relationship of the MBL2 gene with the infection." (PMID 31652745, 2019). "The MBL2*LYPA/LYPA genotype was associated with the absence of asymptomatic infection (P = 0.017), whereas the MBL2*LYQC haplotype and YA/YO + YO/YO genotypes were associated with positive parasite counts in asymptomatic adults (P = 0.033 and 0.018, respectively)." (PMID 19432958, 2009). "The average number of microbiologically documented infections was not statistically significant different between both groups, although there was a greater number of infections with microbiological documentation in the variant MBL2 group: 1.32 (SD = 1.53) versus 0.81 (SD = 0.96 p = 0.1)." (PMID 24886325, 2014). "The mannose-binding lectin 2 (MBL2) gene is one of the members of the C-type (Ca2+ dependent) lectin gene superfamily and plays an important role in the first line of defense against pathogen infection." (PMID 36980927, 2023). "In Asutsuare, the MBL2 54 GA genotype had significantly higher odds of supporting asymptomatic infections compared to no infection (p=0.021)." (PMID 35291755, 2022).
infection (continued). "Markers associated with a protective immune response, such as IL-17A and mannose binding lectin 2 were still significantly upregulated following infection in the antibiotic-treated mice, despite the lack of protection." (PMID 34011991, 2021). "In addition, several other polymorphisims of MBL2 and SFTPD gene, despite those being analyzed in our study, have been proved and described as functionally important in other diseases and recurrrent infections." (PMID 33679736, 2021). "Additionally, the expression of transforming growth factor beta 1 (TGF-β1) and mannose-binding lectin 2 (MBL2) have been identified as gene modifiers for CF and infection severity." (PMID 32630625, 2020). "This prospective study focused on analysing the influence of MBL2 polymorphisms and MBL serum levels in the incidence of infections and outcome of myeloablative and non-myeloablative Allo-HSCT patients." (PMID 31706269, 2019). "Through further analysis, we identified a significant difference in the C7 and MBL2 genotypes between the patient groups with and without infection." (PMID 27063552, 2016). "The incidence, severity of infections and mortality in 72 consecutive patients with hematologic diseases who underwent ASCT between February 2006 and June 2008 in a tertiary referral center were analyzed according to their MBL2 genotype." (PMID 24886325, 2014). "Genotype AA of the MBL2 gene was the most common, but no significantdifferences were observed in the genotypic and allelic frequencies between the threegroups investigated, even whencomparing the presence of markers of past infections by C. trachomatisand C. pneumoniae." (PMID 27982280, 2016).
tumor (32 papers, 2013 to 2026). "MBL2 is implicated in the host immune response, indicating potential crosstalk between MBL2 and the immune cell infiltration of the tumor microenvironment." (PMID 37835594, 2023). "A bioinformatics analysis revealed close relationships among MBL2 downregulation, the tumor-associated proliferation and metastasis pathway, and tumor immunosuppressive microenvironments." (PMID 37835594, 2023). "Therefore, we analyzed the association between MBL2 and lymphocytes in the tumor microenvironment." (PMID 37835594, 2023). "Mannose-binding lectin 2 (MBL2), a member of the multimeric lectin family, is crucial in immune regulation and tumor development." (PMID 37835594, 2023). "Previous studies have indicated the significant involvement of MBL2 in tumor development, including HCC." (PMID 37835594, 2023). "Tumor growth curves and weights showed that tumor growth was inhibited in the MBL2 group relative to that in the control group." (PMID 37835594, 2023). "We analyzed the correlation between MBL2 and tumor-infiltrating lymphocytes in the tumor microenvironment and the relationship between potential upstream microRNAs (miRNAs) and the dysregulation of MBL2." (PMID 37835594, 2023). "High MBL2 expression was correlated with antitumor immune cells, including natural killer cells and CD8 T cells, indicating a close relationship between low MBL2 expression and tumor immune escape." (PMID 37835594, 2023). "MBL2 is an activator of the lectin pathway and a crucial component of the innate immune system, and inflammatory reactions are critical for tumor progression and can promote human carcinogenesis." (PMID 34944885, 2021). "Moreover, MBL2 expression was regulated by miR-34c-3p, as confirmed by the dual-luciferase reporter assay, thereby demonstrating tumor progression in HCC cells." (PMID 37835594, 2023). "MBL2, a calcium-dependent factor, can initiate the complement lectin pathway to induce lysis and opsonophagocytosis by binding to mannose and other oligosaccharide structures on the surface of pathogens, apoptotic cells, and some tumor cells." (PMID 35590261, 2022). "In patients, low MBL2 expression was associated with shorter survival, but no impact on tumour recurrence was noted." (PMID 35326694, 2022). "However, the highest frequency of the A/G (MASP2) and LXA/O or O/O (MBL2) genotypes was found among OC patients with tumours of G1–2 grade (well/moderately differentiated).Furthermore, MBL deficiency-associated genotypes predicted prolonged survival." (PMID 25038892, 2014). "Therefore, we can consider that the altered HCC risk caused by MBL2 polymorphisms were not triggered by its anti-tumor activity but due to the mutant MBL2 protein failed to activate complement system, and eventually lead to the deficiency of innate immunity." (PMID 27557564, 2016). "IHC analysis of paired tumour tissue samples from 10 patients confirmed the expression of four markers (BTD, ECM1, MBL2, and RAB5C) in both blood and tissues, as demonstrated in our study." (PMID 40545963, 2025). "To investigate the effect of MBL2 on HCC cell growth in vivo, we constructed a subcutaneous tumor model in nude mice." (PMID 37835594, 2023). "MBL2 is closely related to CTC formation and is a potent marker of tumor micrometastases and progression." (PMID 37835594, 2023). "The result showed that the lower mRNA expressions of C3, C5, CFB, and CLU were correlated with more advanced cancer stage, while the lower mRNA expressions of C1S, C8B, CFI, MBL2, and C4BPA were correlated with higher tumor grade in HCC patients." (PMID 34813686, 2022). "Longitudinal analysis showed that the expression of IGHV4-39 possessed a similar trend, while MBL2 and LTA showed an opposite trend to tumor size, which may have the potential to predict cancer recurrence after therapy." (PMID 38349411, 2024).
tumor (continued). "MBL2 expression had a negative influence on tumor purity and the immunosuppressive microenvironment was infiltrated by MDSC, CAF, dendritic cells, and Tregs." (PMID 37835594, 2023). "In addition, the mRNA expressions of C1S, C8B, MBL2, CFI, and C4BPA were correlated with tumor grade and prognosis in HCC patients." (PMID 34813686, 2022). "Furthermore, in contrast to ficolin genes, the ovarian expression of MBL2 and MASP2 was significantly higher in ovarian sections from malignant tumours compared with benign tumours or normal tissue." (PMID 35326694, 2022). "The correlation analysis of the expression of GSTA2 and the identified ROS-associated genes using the LIHC database in the GEPIA web server revealed that the expression level of GSTA2 was significantly correlated with ALB, TPO, APOE, MBL2, and FTH1 in the tumor tissues." (PMID 34290233, 2021). "Lnc-MBL2-4:1 (OTTHUMT00000048111) was detectable in 3% (1/32) tumor tissue samples and was not detectable in all the normal tissue samples." (PMID 25045670, 2014).